RPL7AP28 (ribosomal protein L7a pseudogene 28)
Synonyms: RPL7A_10_519
Gene: Transcribed processed pseudogene on chromosome 4 (131,857,343 to 131,857,913, reverse strand). Ensembl gene ENSG00000184139.
Diseases named in the same sentence as RPL7AP28 in open-access papers:
RPL7AP28 is named in the same sentence as 1 disease in open-access papers, as found by Europe PMC text mining. Sharing a sentence is not in itself a finding about the gene and the disease. The quoted sentences say what the papers report.
osteosarcoma (1 paper, 2021). A usually aggressive malignant bone-forming mesenchymal neoplasm, predominantly affecting adolescents and young adults. "New signatures of four pseudogenes, RP11-326A19.5, RP4-706A16.3, RPL7AP28, and RPL11-551L14.1, for osteosarcoma were found, which is a promising independent survival predictor and serves as an important biomarker for clinical treatment of osteosarcoma to improve patient management." (PMID 34947885, 2021).